CAV1 (caveolin 1)
Diseases named in the same sentence as CAV1 in open-access papers (continued):
Sharing a sentence is not in itself a finding about the gene and the disease.
colitis (11 papers, 2012 to 2025). Inflammation of the colon. "Compared with the WT mice, the reduction in expression of the epithelial barrier marker protein ZO-1 was less pronounced in DSS-induced experimental colitis mice with CAV1 deficiency mice." (PMID 40877233, 2025). "There it was observed that Cav-1 was up-regulated during dextran sodium sulphate (DSS)-induced murine colitis and a loss of Cav-1 significantly protected against inflammatory tissue damage." (PMID 25756273, 2015). "However, in contrast to its role in the endothelium, CAV1 deficiency has been shown to exacerbate DSS-induced colitis and contribute to the prevention of intestinal nitrosative stress and mucosal barrier damage." (PMID 40877233, 2025). "However, we noted an elevation in p-MLKL levels in CAV1-deficient colitis mice, suggesting a potential link between CAV1-induced epithelial demise and necroptosis." (PMID 40877233, 2025). "EC-specific re-expression of Cav-1 in Cav-1 KO mice, such as that done in Chidlow’s murine model of pathological angiogenesis associated with drug-induced experimental colitis could possibly help to explain these differences." (PMID 26605130, 2012). "Consistent with the organoid experiment, a genetic defect of CAV1 could rescue the epithelial necroptosis caused by DJ-1 deficiency, indicating that the DJ-1/CAV1/necroptosis pathway participated in the pathogenesis of colitis." (PMID 40877233, 2025). "Utilizing necroptosis-modeled organoids from murine intestines and pharmacological inhibition of necroptosis, our findings demonstrated that the DJ-1/CAV1 pathway governed epithelial inflammation via necroptosis in the context of colitis." (PMID 40877233, 2025). "Overall, our findings establish for the first time that DJ-1 promotes CAV1 degradation to inhibit the disruption of the epithelial barrier and protect against necroptosis in colitis." (PMID 40877233, 2025). "To mechanistically verify the contribution of epithelial CAV1 to colitis, we examined the relationship between CAV1 and DJ-1." (PMID 40877233, 2025). "In this investigation, we delineated the involvement of CAV1 in murine models of dextran sulfate sodium (DSS)-induced colitis." (PMID 40877233, 2025). "To verify the clinical value of CAV1 and necroptosis in colitis, we collected intestinal samples from IBD patients and observed that CAV1 and p-MLKL were both significantly increased in advanced UC and CD patients compared with healthy controls." (PMID 40877233, 2025). "To determine the cell populations that contribute to CAV1-mediated inflammation in colitis, we generated CAV1 KO bone marrow chimeras." (PMID 40877233, 2025). "This study is the first to identify DJ-1 as a mediator of CAV1, suggesting that the pivotal role played by CAV1 in triggering necroptosis ultimately results in epithelial inflammation in colitis." (PMID 40877233, 2025). "Subsequent mechanistic analyses revealed that the colitis-protective protein DJ-1 regulated CAV1 through a proteasome-mediated protein degradation pathway." (PMID 40877233, 2025). "CAV1 serves as the principal architectural constituent of caveolae in endothelial cells, and it has been documented that endothelial CAV1 plays a pivotal role in regulating colitis." (PMID 40877233, 2025). "Several studies have reported generation of DSS colitis models in CAV1 KO mice, but the results are controversial." (PMID 40877233, 2025). "Taken together, our research demonstrated the key role of CAV1 in colitis and revealed the mechanism by which CAV1 promoteed epithelial necroptosis, leading to impairment of the epithelial barrier." (PMID 40877233, 2025). "In summary, our research revealed that epithelial CAV1 aggravated necroptosis in experimental colitis, leading to impairment of the epithelial barrier, which was negatively regulated by DJ-1." (PMID 40877233, 2025). "This connection between ClC-2, occludin, and caveolin-1 was further supported in vivo with a model of DSS-induced colitis." (PMID 32024112, 2020).
colitis (continued). "2,4,6-Trinitrobenzenesulfonic acid-induced colitis is T cell-dependently regulated, leading to Cav-1 suppression." (PMID 32461676, 2020). "Recently, we demonstrated that endothelial caveolin-1 plays a key role in the pathological angiogenesis of dextran sodium sulfate (DSS) colitis." (PMID 35013693, 2020). "We have found that in TNBS-induced colitis, colon Cav-1 levels are reduced and inversely correlated with colon inflammation and pro-inflammatory cytokine levels significantly." (PMID 25756273, 2015). "There are possible explanations for these opposing findings of the role of Cav-1 in experimental mouse colitis in the two studies." (PMID 25756273, 2015). "Both this previous study and our current studies used Cav-1 knockout mice to explore the role of Cav-1 in colitis." (PMID 25756273, 2015). "Employing a TNBS-induced murine colitis model, we induced both acute and chronic colitis in Balb/c mice and acute colitis in C57BL/6J Cav-1-/- and wild-type mice." (PMID 25756273, 2015). "In Cav-1(−/−) mice or mice given Cav-1 inhibitory peptide, the colitis histopathology scores, vascular densities, and levels of inflammatory infiltrates decreased significantly compared with controls." (PMID 26839731, 2015). "Colon Cav-1 levels were significantly decreased in TNBS-induced colitis mice when compared to normal mice and also inversely correlated with colon inflammation scores and proinflammatory cytokine levels (IL-17, IFN-γ and TNF) significantly." (PMID 25756273, 2015). "Mice receiving TNBS had significantly decreased Cav-1 levels (P < 0.0001 in chronic colitis) compared to that reported in the DSS-induced colitis model." (PMID 25756273, 2015). "In a previous report, in DSS-induced mouse colitis, compared with normal mice, Cav-1 levels were increased, and genetic deletion (Cav-1-/- mice) or pharmacologic inhibition of Cav-1 significantly decreased vascular density and angiogenesis scores." (PMID 25756273, 2015). "Specifically, angiogenesis was markedly reduced in global Cav-1 KO mice relative to WT mice with pharmacologically-induced colitis." (PMID 26605130, 2012). "Thus, it is possible that TRAF4 acts as a key upstream regulator of CAV1 expression in colitis; however, definitive confirmation necessitates additional experimental evidence." (PMID 40877233, 2025). "Hence, further studies are required to elucidate the possible mechanisms involved in the DJ-1/CAV1/necroptosis pathway in colitis." (PMID 40877233, 2025). "Moreover, in the mice with DSS-induced colitis, there was an accumulation of CAV1 protein expression compared to that in the control mice." (PMID 40877233, 2025). "Furthermore, we found that necroptosis was downstream of DJ-1/CAV1 in DKO mice with colitis and organoids." (PMID 40877233, 2025). "Here, we aimed to address the question of the role of CAV1 in colitis and whether the pathogenesis of CAV1 is dependent on necroptosis." (PMID 40877233, 2025). "To confirm the role of CAV1 in colitis, we repeated the same experiment." (PMID 40877233, 2025). "Thus, CAV1 plays a pivotal role in the pathogenesis of colitis; however, its precise function remains subject to debate and ambiguity." (PMID 40877233, 2025). "This pathway could potentially be an unrecognized mechanism of CAV1 and shed light on the diagnosis and therapies of colitis." (PMID 40877233, 2025). "Caveolin-1 (CAV1), a main component of cholesterol-rich caveolae domains of endothelial plasma membranes, has been suggested to mediate pathologic angiogenesis in a mouse model of colitis." (PMID 35805947, 2022).
colitis (continued). "In contrast with the adverse activity of Cav-1 in the present model, a previous investigation using a 2,4,6-trinitrobenzenesulfonic acid-induced colitis model suggested that Cav-1 played protective roles against intestinal inflammation with no molecular evidence of its effects." (PMID 32461676, 2020). "In the present study, we further clarified the role of Cav-1 in TNBS-induced colitis." (PMID 25756273, 2015). "So, it was concluded endothelial Cav-1 mediates angiogenesis in experimental colitis, suggesting that Cav-1 might be a novel therapeutic target for IBD." (PMID 25756273, 2015). "Thus, as we have seen in TNBS-induced experimental colitis, a decrease in Cav-1 levels results in a higher TNF output, possibly due to a loss of TLR4 regulation." (PMID 25756273, 2015). "Thus, our original plan was to develop a vaccine targeting Cav-1 and, hopefully, alleviating colitis symptoms." (PMID 25756273, 2015). "Until now, only one study reported the role of Cav-1 in experimental colitis." (PMID 25756273, 2015). "However, other studies have shown that CAV1 protects against DSS-induced colitis." (PMID 40877233, 2025). "However, in active colitis, CAV1 was a harmful factor in IBD." (PMID 40877233, 2025). "Therefore, prolonged Cav-1 induction may retard epithelial restitution, resulting in further luminal infection in the gut epithelium of patients with IBD or colitis-associated malignancy." (PMID 32461676, 2020). "Cav-1 may play a protective role in the development of TNBS-induced colitis." (PMID 25756273, 2015). "Thus, Cav-1 might actually play a protective role in TNBS-induced colitis, which deserves to be explored further." (PMID 25756273, 2015). "As both reports of TNBS- and DSS-induced colitis studied Cav-1 knockout mice, providing evidence of opposite effects, it is critical to be aware that in the evaluation of specific molecules in animal models, there may be opposite results dependent on the pathogenetic mechanisms that are involved." (PMID 25756273, 2015). "CAV1 KO mice and their WT littermates were treated with 3.5% DSS to establish an acute experimental colitis model." (PMID 40877233, 2025). "Thus, we concluded that Cav-1 may play an important role in protection from TNBS-induced colitis." (PMID 25756273, 2015). "In this study, we examined how the antennapedia- (AP-) conjugated caveolin-1 scaffolding domain (AP-Cav) modulates vascular endothelial growth factor- (VEGF-) dependent colon endothelial cell angiogenic responses, as seen during colitis." (PMID 35013693, 2020). "A recent study showed that Cav-1 is increased and mediates angiogenesis in dextran sodium sulphate-induced colitis, which are contradictory to our pilot findings in 2,4,6-trinitrobenzene sulphonic acid (TNBS)-induced colitis." (PMID 25756273, 2015). "Taken together, although in T cell-independent colitis, such as DSS-induced colitis, Cav-1 exacerbates the disease, as previously reported, in T cell-dependent colitis induced by TNBS, mice that lack Cav-1 (Cav-1-/-) actually have less severe inflammation compared to controls." (PMID 25756273, 2015). "In the bone marrow suppression experiments, we could only demonstrate that immune cells play no role in CAV1-mediated inflammation in colitis." (PMID 40877233, 2025).
esophageal cancer (11 papers, 2004 to 2021). A primary or metastatic malignant neoplasm involving the esophagus. "The current study indicates that hypermethylation of the CAV1 promoter, leading to gene silencing, is a common event in human esophageal cancer and occurs early during Barrett’s-associated EAC." (PMID 24885118, 2014). "CAV1 promoter hypermethylation is a frequent event in human esophageal carcinomas and is associated with early neoplastic progression in Barrett’s esophagus." (PMID 24885118, 2014). "Although suggested as tumor suppressor gene, and downregulated in some oncogene-transformed and tumor-derived cells, overexpression of CAV1 has been found in prostate and esophageal cancer." (PMID 18694510, 2008). "Therefore, we hypothesized that CAV1 was inactivated via promoter hypermethylation in human esophageal cancers, and that hypermethylation of CAV1 constituted an early event in the genesis of EAC." (PMID 24885118, 2014). "Besides, molecules, like Caveolin-1, Ezrin, and LAMP3, were also checked in esophageal carcinoma tissues." (PMID 34178655, 2021).
head and neck squamous cell carcinoma (11 papers, 2008 to 2025). A squamous cell carcinoma that arises from any of the following anatomic sites: lip and oral cavity, nasal cavity, paranasal sinuses, pharynx, larynx, and salivary glands. "In this study, we aimed to explore the pathogenic and prognostic roles of CAV1 and CAV2 in head and neck squamous cell carcinoma (HNSCC) through bioinformatic analysis and verified in human tissue." (PMID 36830672, 2023). "CAV1 can promote cancer progression via inhibiting ferroptosis in head and neck squamous cell carcinoma and drives the execution of acute immune-mediated hepatic damage." (PMID 35242169, 2022). "High levels of CAV1 inhibit ferroptosis in head and neck squamous cell carcinoma." (PMID 40180904, 2025). "Moreover, CAV1 also increases cancer progression by inhibiting ferroptosis in head and neck squamous cell carcinoma." (PMID 37642765, 2023). "Evidence suggests that miRNA-133a may act as an upstream regulator of CAV1 expression in head and neck squamous cell carcinoma (HNCC) as the expression of miRNA-133a is down-regulated while CAV1 is up-regulated in HNCC." (PMID 26112043, 2015).
liver cancer (11 papers, 2014 to 2025). An epithelial or non-epithelial malignant neoplasm that arises from the liver. "Mechanistically, Cav-1 has been shown to associate with IKKβ leading to NFkB activation in liver cancer cells." (PMID 31685812, 2019). "Furthermore, Cav-1 deficiency or overexpression of Cav-1 (mutants) as well as dysregulation of caveolar function have been closely related to disease pathogenesis of liver cancer, metabolic adaptation, liver regeneration and lipotoxicity." (PMID 29211809, 2017). "Immunofluorescence analysis of sequential tumour biopsies of HCC patients further confirmed increased CAV1 expression in liver cancer cells following disease recurrence." (PMID 40715090, 2025). "Given the increasing number of cases of liver cancer, nonalcoholic steatohepatitis, and non-alcoholic fatty liver disease worldwide, investigations on the role of Cav1 in liver diseases are warranted." (PMID 34434195, 2021). "At early stages, CAV1 has been ascribed roles as a tumor suppressor in colorectal, breast, lung, and liver cancers." (PMID 32458269, 2020). "Treatment with DNA-hypomethylating agents, such as 5-aza-2′-deoxycytidine, restores the expression of CAV1, not only in breast and prostate but also in ovarian, colon, and liver cancer cells." (PMID 32458269, 2020). "For instance, CAV1 expression in liver cancer patients was found to positively correlate with differentiation status, increased portal vein invasion, intrahepatic metastasis, and to predict overall survival outcome." (PMID 27852311, 2016). "Consistently, and contrary to its tumour promoting function highlighted above, high CAV1 expression improved overall survival in liver cancer patients, ostensibly by countering eNOS activity." (PMID 27852311, 2016). "Overexpression of CAV1 promoted liver cancer cell motility and invasiveness in vitro, as well as metastasis in vivo." (PMID 25180681, 2014). "Interestingly, however, CAV1 has also been shown to promote tumor development by regulating Ca2+ homeostasis in breast, stomach, lung, colon, and liver cancers." (PMID 32458269, 2020). "The reduction of the ubiquitination of CAV1 and TGF-β receptors by the deubiquitinase POH1 reduces lysosomal degradation of the TGF-β receptors in liver cancer cells." (PMID 32458269, 2020). "To investigate the clinical relevance of CAV1, CD47 and FLNC we analysed the transcriptomic data from 67 HCC cases in the Biostorm cohort of the Storm trial, a phase 3 clinical study exploring sorafenib as an adjuvant therapy in liver cancer patients who had previously had local ablation surgery." (PMID 40715090, 2025).
rhabdomyosarcoma (11 papers, 2011 to 2024). A rare aggressive malignant mesenchymal neoplasm arising from skeletal muscle. "Differential expression levels of caveolin-1 have been correlated with myogenic differentiation of rhabdomyosarcoma." (PMID 31252633, 2019). "The Cav-1 expression was found either undetectable or very low in alveolar rhabdomyosarcomas cell lines and tumor samples, whereas Cav-1 reintroduction impaired cells clonogenic capacity and promoted features of muscular differentiation." (PMID 26431273, 2015). "In this study we show that Cav-1 was phosphorylated on tyrosine 14 (pCav-1) by Src-kinase family members in various human cell lines and primary mouse cultures of rhabdomyosarcoma (RMS), the most frequent soft-tissue sarcoma affecting childhood." (PMID 24427291, 2014). "In the present study we report that compared to other forms of rhabdomyosarcoma (RMS) CAV1 expression is either undetectable or very low in ARMS cell lines and tumor samples." (PMID 25313138, 2014). "A previous study showed that ferroptosis susceptibility was enhanced by increased ERK pathway activation due to CAV1 overexpression in human rhabdomyosarcoma cells, and antioxidant molecules such as GSH could alleviate ferroptosis." (PMID 36506045, 2022). "The relevance of CAV1 tyrosine 14 phosphorylation has also been studied in rhabdomyosarcoma." (PMID 35158857, 2022). "Similarly to studies in other cancer cell lines, Src kinase was shown to phosphorylate CAV1 in human and mouse rhabdomyosarcoma cell lines." (PMID 35158857, 2022). "On the other hand, most alveolar rhabdomyosarcoma tumors exhibiting advanced degree of maturation had very low levels of CAV1 suggesting that CAV1 might be a tumor suppressor in alveolar rhabdomyosarcomas." (PMID 21471610, 2011).
atrial fibrillation (10 papers, 2013 to 2025). A disorder characterized by an electrocardiographic finding of a supraventricular arrhythmia characterized by the replacement of consistent P waves by rapid oscillations or fibrillatory waves that vary in size, shape and timing and are accompanied by an irregular ventricular response. "rs3807989 is located in an intron on the Caveolin-1 (CAV1) gene, whichis associated with PR interval and atrial fibrillation in European populations." (PMID 39076272, 2023). "Atrial fibrillation was associated with decreased CAV1 in right and left atria (p = 0.03); Loss of CAV1 leads to cSrc tyrosine kinase activation, gap junction remodeling, and ventricular arrhythmia, slowing left ventricular conduction velocity, and increasing ventricular arrhythmia inducibility." (PMID 35498046, 2022). "Furthermore, Cav1.3−/− mice display impaired Ca2+ homeostasis associated with atrial fibrillation (AF)." (PMID 37025382, 2023). "Four SNPs near genes PITX2, ZFHX3, CAV1, and SYNPO2L are significantly linked with atrial fibrillation (AF), a significant stroke risk factor." (PMID 40863347, 2025).